RARA (retinoic acid receptor alpha)
Diseases named in the same sentence as RARA in open-access papers (continued):
Sharing a sentence is not in itself a finding about the gene and the disease.
Obesity (6 papers, 2014 to 2024). Accumulation of substantial excess body fat. "Given the reduced VA in obesity-related diseases, a potentially novel therapeutic approach is the use of highly selective agonists for RARα, β, and γ." (PMID 30677086, 2019). "Am580, a selective agonist of RARα, is not an activator of PPARβ/δ, and thus, the mechanisms whereby Am580 regulates cardiac lipid metabolism and suppresses obesity may be different than those of ATRA." (PMID 26237391, 2014).
osteosarcoma (6 papers, 2020 to 2024). A usually aggressive malignant bone-forming mesenchymal neoplasm, predominantly affecting adolescents and young adults. "In addition, the target of ATRA, retinoic acid receptor α (RARα), is stabilized by SUMOylation at K399; and mutation of K399 of RARα impairs ATRA-induced osteosarcoma cell differentiation." (PMID 36078118, 2022). "It is known that all-trans retinoic acid (ATRA) induces differentiation of osteosarcoma cells regulated by retinoic acid receptor alpha (RARα), and RARα can be degraded through the ubiquitin–proteasome pathway to inhibit osteosarcoma cell differentiation." (PMID 39062505, 2024). "In “Myeloid”, differentially expressed NRs such as NR4A2, NR4A1, NR3C1, RXRA, NR1D2, PPARD, and RARA were identified among metastasis, primary, and recurrent osteosarcoma tissues." (PMID 35965537, 2022). "These suggest that SUMO1 acts as an anti-osteosarcoma molecule by targeting RARα." (PMID 36078118, 2022). "Previous reports indicated that RARαS77A, a phosphorylation-defective mutant of RARα, could mimic RARα hypo-phosphorylation and inhibit the proliferation of human squamous carcinoma, osteosarcoma, and AML cells." (PMID 33902658, 2021). "According to our results, the endogenous levels of RARα and VDR could be used as a predictor of possible synergy between ATRA and calcitriol in osteosarcoma cells." (PMID 32916897, 2020). "In general, the results suggest that the levels of RARα and VDR in osteosarcoma cells could potentially be used as predictors of possible synergy between calcitriol and ATRA." (PMID 32916897, 2020). "The antagonists of RARa and RARg exhibit no inhibitory effect on osteosarcoma cell growth." (PMID 36681687, 2023). "Therefore, in addition to RARa activation, whether ATRA-mediated inhibition of osteosarcoma cell growth may also be partially attributed to RARg activation requires further study." (PMID 36681687, 2023). "In addition to RARa, RARb and RARg are also thought to be activated by ATRA in osteosarcoma cells." (PMID 36681687, 2023). "For better interpretation, we compared the two most different osteosarcoma cell lines—the Saos-2 reference cell line, which had the lowest level of RARα and the highest level of VDR, and the OSA-08 cell line, which had the highest level of RARα and the lowest level of VDR." (PMID 32916897, 2020).
pancreatic cancer (6 papers, 1998 to 2025). "Moreover, the expression of RARα and RXRβ is associated with higher OS in pancreatic cancer patients." (PMID 39850424, 2025). "The authors employed the pancreatic tumor cell lines PaTu8988-S and PaTu8988-T and administered 1 μmol/L ATRA or a selective RARα antagonist for 72 h." (PMID 31470825, 2019). "In addition, our database analyses showed that the expression of RARα was increased in pancreatic cancer, similar to that of RARγ, and that patient prognosis correlated with RARγ expression but not with RARα expression." (PMID 37198667, 2023).
lung adenocarcinoma (5 papers, 2009 to 2024). A carcinoma that arises from the lung and is characterized by the presence of malignant glandular epithelial cells. "Another study of retinoic acid reported that increased RARα and RARγ could mediate growth inhibition by all-trans retinoic acid (ATRA) in H1792 cells, a lung adenocarcinoma cell line." (PMID 33735188, 2021). "Further, both shRNA and siRNA knockdown of RIP140 enhanced RA induction of RARB but not RARA in the RA-responsive murine lung adenocarcinoma line, ED-1 (data not shown)." (PMID 19862326, 2009).
metastatic disease (5 papers, 2018 to 2024). "The high levels of RARα, RARβ and RXRα determined in our tumor tissues associated with unfavorable clinical factors such as relapsed and “de novo” metastatic disease." (PMID 39323992, 2024). "In summary, the immunoexpression of RARA and CRABP2 was increased in samples from patients subjected to pre-surgical chemotherapy and in samples from patients with metastatic disease, respectively." (PMID 29378601, 2018).
neuroblastoma (5 papers, 2013 to 2022). Neuroblastoma (NB) is the most common solid, extracranial childhood tumor. "In this study, we first found that the selective agonist AM580 can induce the SH-SY5Y differentiation, suggesting the activation of RARα is enough to promote neuroblast to neuron (at least in neuroblastoma cell line SH-SY5Y)." (PMID 36066699, 2022). "ZNF423 has previously been described as a transcriptional cofactor of RARα/RXRα that is critically required for retinoic acid-induced differentiation of neuroblastoma." (PMID 31234811, 2019). "Upon treatment, ATRA binds to RARA, which binds to RXR, and the complexes bind to retinoid response elements coordinately with other members of the retino-sympathetic CRC to activate the expression of genes associated with neuroblastoma differentiation." (PMID 34669465, 2021). "Moreover, ZNF423 was previously reported to act as a co-activator of RARα/RXRα heterodimers in neuroblastoma cells." (PMID 31284679, 2019). "Thus, ATRA initiates a change in cell state of neuroblastoma cells corresponding to a shift from the adrenergic CRC to a new retino-sympathetic CRC, which includes RARA, HAND2, ISL1, TBX2, TBX3, MEIS1, and SOX4." (PMID 34669465, 2021).
colorectal cancer (4 papers, 2017 to 2025). A primary or metastatic malignant neoplasm that affects the colon or rectum. "When overexpressed, RARA is found to be associated with worse survival rates in colorectal cancer patients." (PMID 35428183, 2022). "The role of EGFR and RARA in 5-fluorouracil (5-FU) resistant COAD (colorectal cancer) cells was analyzed." (PMID 31896739, 2020). "Retinoids involving ATRA also improves the antitumor immunity in microbiota-induced colorectal cancer, as it increases the efficacy of tumor-specific cytotoxic T-lymphocytes by increasing RARα-mediated MHCI expression in tumor cells." (PMID 28458670, 2017). "RARA and EGFR were associated with worse survival in colorectal cancer patients." (PMID 31896739, 2020).
diabetes (4 papers, 2014 to 2022). "Using an in vivo type 2 diabetic animal model, we provided additional evidence supporting a role of RARα and RXRα in the diabetes-induced development of cardiac remodeling." (PMID 26237391, 2014). "Based on these data, it is likely that diabetes-induced oxidative stress and activation of JNK promotes degradation and transcriptional inhibition of RARα and RXRα, through phosphorylation of RARα and RXRα at specific phosphorylation sites." (PMID 26237391, 2014).
dyslipidemia (4 papers, 2018 to 2023). "The two upstream regulators—RARA and NKX2-3—appear to play a key role in controlling gene expression in HFD-MSCs and are important for adipocyte metabolism and differentiation; their dysregulation can contribute to metabolic syndrome and inflammation." (PMID 33361524, 2020).
Fibroadenoma (4 papers, 2011 to 2025). A benign tumor of the breast characterized by the presence of stromal and epithelial elements. "In a recent study, exome sequencing of 22 PTs and targeted sequencing of 100 fibroepithelial neoplasms revealed the genetic profile of fibroepithelial neoplasms, with MED12 (73%) and RARA (32%) mutations common in fibroadenoma patients and in all pathologically classified PTs' patients." (PMID 37771427, 2023). "Expression of both RARα and RARβ were highest in fibroadenoma tissue." (PMID 21283523, 2011). "Total RNA extracted from malignant (n = 75), normal (n = 15), and fibroadenoma (n = 10) breast tissue biopsies was analysed using RQ-PCR targeting NIS, RARα, RARβ, ERα, PI3K, THRα and THRβ." (PMID 21283523, 2011). "Human breast tissue specimens (malignant n = 75, normal n = 15, fibroadenoma n = 10) were analysed by RQ-PCR targeting NIS, receptors for retinoic acid (RARα, RARβ), oestrogen (ERα), thyroid hormones (THRα, THRβ), and also phosphoinositide-3-kinase (PI3K)." (PMID 21283523, 2011).
juvenile myelomonocytic leukemia (4 papers, 2013 to 2022). A myelodysplastic/myeloproliferative neoplasm of childhood that is characterized by proliferation principally of the granulocytic and monocytic lineages. "In 2007, the FIP1L1/RARA fusion gene was first reported as a novel RARA-associated fusion gene in a patient with juvenile myelomonocytic leukemia (JMML)." (PMID 34249738, 2021). "The FIP1L1::RARA fusion gene was first reported as a novel RARA-associated fusion gene in a 20-month-old child with juvenile myelomonocytic leukemia (JMML), no other mutations in N-Ras, K-Ras, or PTPN11 were detected." (PMID 36776354, 2022). "Interestingly, the same FIP1L1-RARA transcript, whose breakpoint was at exon-15 of FIP1L1 and the exon-3 of RARA, generated not only APL but also juvenile myelomonocytic leukemia, indicating the plasticity of FIP1L1-RARA-positive leukemic initial cells." (PMID 33957999, 2021).
thyroid cancer (4 papers, 2021 to 2025). "In vivo experiments in nude mice confirmed our conjecture, indicating that LBX2-AS1 modulated the expression of FSTL3 by recruiting RARα to accelerate the progression of thyroid cancer." (PMID 34858481, 2021). "Subsequently, through cell experiments, molecular experiments, and in vivo experiments, it was unveiled that LBX2-AS1 boosts the transcriptional activity of FSTL3 by recruiting the binding of RARα, thereby hastening progression of thyroid cancer cells." (PMID 34858481, 2021). "Bioinformatics analysis found that RARα was evidently elevated in thyroid cancer tissue and it was positively correlated with LBX2-AS1." (PMID 34858481, 2021). "Subsequently, molecular experiments, cell experiments and animal model experiments confirmed that lncRNA LBX2-AS1 can recruit the TF RARα to foster the expression of FSTL3 to boost development of thyroid cancer." (PMID 34858481, 2021). "At the same time, the RPISeq database score indicated that LBX2-AS1 interacted with RARα with high reliability, and RARα was prominently boosted in thyroid cancer tissue." (PMID 34858481, 2021). "Our study revealed that the lncRNA LBX2-AS1/RARα/FSTL3 axis may affect the progression of thyroid cancer through bioinformatics method." (PMID 34858481, 2021). "Collectively, this study uncovered the LBX2-AS1/RARα/FSTL3 modulatory axis in thyroid cancer." (PMID 34858481, 2021). "In this study, combined with the bioinformatics analysis and research of predecessors, it was speculated that LBX2-AS1 modulated the expression of FSTL3 by recruiting RARα to hasten the progression of thyroid cancer." (PMID 34858481, 2021). "The rescue experiments showed that LBX2-AS1 recruited the TF RARα to hasten the transcription activity of FSTL3 and thus promoted the development of thyroid cancer." (PMID 34858481, 2021). "LBX2-AS1 upregulates the expression of FSTL3 by recruiting RARα to the FSTL3 promoter, which suggests that FSTL3 may play a role in accelerating the progression of thyroid cancer." (PMID 36325361, 2022). "Combining the previous research and bioinformatics research results, this study speculated that the lncRNA LBX2-AS1/RARα/FSTL3 axis can affect the development and progression of thyroid cancer." (PMID 34858481, 2021).
viral infection (4 papers, 2016 to 2025). "The expression of RA-regulated genes, such as RARA, RARB, CRABP1, HOXB1, and STRA6, were all downregulated after HSV-1 infection, thus further demonstrating that RA synthesis was inhibited by viral infection." (PMID 38989466, 2024).
atherosclerosis (3 papers, 2021 to 2022). A disease characterized by the build-up of fatty material and calcium deposition in the arterial wall resulting in partial or complete occlusion of the arterial lumen. "Since macrophage cholesterol efflux is the first step in RCT and is critical in preventing atherogenesis, macrophage RARα deficiency promotes the development of atherosclerosis likely through, at least in part, inhibiting cholesterol efflux." (PMID 36291054, 2022). "Thus, macrophage RARα deficiency promotes the development of atherosclerosis, likely via inhibition of macrophage cholesterol efflux and induction of macrophage inflammation." (PMID 36291054, 2022). "The increased macrophage inflammatory response may play a role in the progression of atherosclerosis in RARα-deficient mice." (PMID 36291054, 2022). "Our data demonstrate that macrophage RARα protects against atherosclerosis, likely via inducing cholesterol efflux and inhibiting inflammation." (PMID 36291054, 2022). "In the current study, we investigated the role of macrophage RARα in the development of atherosclerosis." (PMID 36291054, 2022). "In this work, we show that macrophage-specific RARα plays a key role in regulating macrophage cholesterol efflux, inflammation, and atherosclerosis." (PMID 36291054, 2022). "It has been reported that cardiac impairment of RARA would lead to the developmentof diastolic dysfunction, while activatedRARA would protect artery from atherosclerosis by derepressing miR-10a in vascularendothelial cells in oscillatory shear regions." (PMID 37101540, 2022). "In summary, we have identified a novel role of macrophage RARα in regulating cholesterol efflux, inflammation, and atherosclerosis." (PMID 36291054, 2022). "However, the role of retinoic acid receptor alpha (RARα) in atherosclerosis remains to be determined." (PMID 36291054, 2022). "Thus, targeting RARα may represent a novel and promising strategy for the treatment of atherosclerosis." (PMID 36291054, 2022). "Thus, it will be interesting to investigate whether AM580 inhibits the development of atherosclerosis by activation of RARα." (PMID 36291054, 2022). "So far, no genetic RARα models have been used for studying the role of RARα signaling in atherosclerosis." (PMID 36291054, 2022). "The role of RARα in atherosclerosis has not been investigated before." (PMID 36291054, 2022).
chronic lymphocytic leukemia (3 papers, 2021 to 2025). "J. Ott and colleagues identified a SE-based CRC in chronic lymphocytic leukemia (CLL) involving PAX5, FOXP1, RARA, ETS1, IRF2, and IRF8, highlighting PAX5's dominant role." (PMID 40083704, 2025). "The success stories with targeted therapies directed against PML::RARA and BCR::ABL in acute promyelocytic and chronic lymphocytic leukemia, respectively, but also the more recent clinical experience with inhibitors of kinase fusion proteins found in sarcoma, underscore this notion." (PMID 38611033, 2024).
colitis (3 papers, 2020 to 2023). Inflammation of the colon. "In addition, the level of the retinoic acid and RARA of colitis mice was increased by treating with sodium butyrate." (PMID 34589596, 2021).
Hepatic steatosis (3 papers, 2022). Steatosis is a term used to denote lipid accumulation within hepatocytes. "While adipocyte-specific expression of dominant-negative RARα causes glucose intolerance and hepatic steatosis in mice." (PMID 36291054, 2022). "Differently, our study uncovered the novel molecular mechanisms of Alisol B on hepatic steatosis and lipotoxicity via regulating RARα-PPARγ-CD36 transcriptional cascade." (PMID 35745142, 2022). "RARα in hepatocytes is also shown to protect against liver steatosis." (PMID 36291054, 2022). "For example, as mentioned in Section 3 above, mice expressing a hepatocyte-specific dominant negative RARα that suppresses the signaling of all endogenous RARs develop hepatic steatosis, with impaired capacity for mitochondrial β-oxidation of fatty acids, which can be reversed with RA treatment." (PMID 35406069, 2022). "We discovered the novel mechanism that Alisol B upregulated the disrupted expression of RARα and then decreased CD36 expression via RARα-HNF4α-PPARγ transcriptional cascade, which further alleviated hepatic steatosis, oxidative stress, inflammation, and fibrosis in the liver of NASH mice." (PMID 35745142, 2022). "An early study has identified that RARα overexpression alleviated hepatic steatosis via suppressing HNF4α-regulated PPARγ expression, but whether CD36 is involved in RARα’s regulation on hepatic lipid metabolism is unknown." (PMID 35745142, 2022). "In contrast to the effects of RARβ2 selective agonists on liver steatosis in HFD-induced NAFLD models, the RARα agonist Am 80 exacerbates and the RARγ agonist CD1530 has no major effect on liver steatosis in these models, respectively." (PMID 35406069, 2022).
infertile (3 papers, 2023 to 2024). "However, 25.0% of Rarα−/− females appeared with a closed vaginal phenotype with the swelling of the genital area, which prevented natural mating and caused infertility." (PMID 37041518, 2023). "The deletion of Rarα resulted in 25.0% of females infertility due to vaginal closure, in which the mRNA (Ctnnb1, Bak and Bax) and protein (Cleaved Caspase-3) levels were significantly decreased, and Bcl2 mRNA levels were significantly increased in the vaginas." (PMID 37041518, 2023).
ischemic stroke (3 papers, 2018 to 2024). A stroke disorder caused by obstruction of blood flow to the brain, due to thrombotic (local blood clot formation) or embolic (due to a blood clot or other material traveling from another site) event. "Tamibarotene (Am80), a selective agonist of RARα, has been shown to exert significant inhibitory effects on neuroinflammation after ischemic stroke and intracranial hemorrhage (ICH), thus suggesting the suitability of targeting RARα as a form of stroke therapy." (PMID 35237277, 2022). "Kong suggested that RA may serve as a new therapeutic approach to prevent blood brain barrier (BBB) dysfunction and tPA-induced rat ICH in ischemic stroke, and the protective effect of RA on the BBB was dependent on RARα." (PMID 29534734, 2018).
liver cancer (3 papers, 2016 to 2021). An epithelial or non-epithelial malignant neoplasm that arises from the liver. "For examples, the dynamic expression of RARB, RARG similar with RARA can control the development and proliferation of liver cancer and HOXB8 from HOX family can play a prominent role as a brain tissue biomarker." (PMID 29033978, 2017).